MED1 (mediator complex subunit 1)
Diseases named in the same sentence as MED1 in open-access papers (continued):
Sharing a sentence is not in itself a finding about the gene and the disease.
breast carcinoma (continued). "Although MED1 overexpression itself does not induce mammary tumor formation, we observed significantly promoted tumor onset, growth, metastasis, and elevated primary tumor multiplicity in MMTV-HER2/MMTV-MED1 double-transgenic mice." (PMID 33691110, 2021). "Here we show that MED1, a Mediator subunit in the Middle module of Mediator complex, is overexpressed in breast cancer and is a negative prognostic factor." (PMID 30087366, 2018). "MED1 co-amplifies with HER2 and is overexpressed in about 40-60% of human breast cancer." (PMID 23936234, 2013). "Multiple other genes from the driver subnetworks, including GRB2, MED1, MED24, and EPN3 are also located in the proximity of the same amplicon (between 17q12–25), underscoring the significance of this chromosomal region in HER2+ breast cancer." (PMID 22343619, 2012). "Therefore, to investigate whether the overexpression of BAP1 affects proliferation, metastasis by Med1 protein expression, cell proliferation, and invasion assays were performed in MCF7 breast cancer cells." (PMID 38708315, 2024). "Further, we show that miR-205 can also regulate the phosphorylation/activation of MED1 through downregulating the HER3/PI3K/Akt pathway, thus inhibiting the recruitment of ER cofactors to the target gene promoters and regulating tamoxifen treatment response of breast cancer cells." (PMID 39682180, 2024). "However, the role and molecular mechanisms of miR-205 and its regulation of MED1 in breast cancer and its treatment resistance is not very well understood." (PMID 39682180, 2024). "Similarly, tamoxifen reduced the size of MED1 nuclear condensates in breast cancer cell lines expressing low levels, but not in resistant cells expressing high levels of MED1." (PMID 36483537, 2022). "Together, our data support MED1 as a major player in breast cancer resistance to both HER2- and ER-targeted therapies, and that MED1 and its target genes, such as Jab1, could represent promising targets to overcome the resistance of HER2+/ER+ tumors to these therapies." (PMID 33691110, 2021). "In addition, the ER co-activator Mediator Subunit 1 (MED1) has been found to be a novel critical cross-talk point for the HER2 and ER signaling pathways within the cell and is amplified or overexpressed in more than 50% of all primary breast cancers." (PMID 28045951, 2017).
prostate carcinoma (27 papers, 2013 to 2025). A carcinoma that arises from epithelial cells of the prostate gland. "The only reported cases of Med1 association with human disease are the overexpression of Med1 in tissues of breast and prostate cancers." (PMID 27548259, 2016). "Importantly, AR activity that was restored in enzalutamide-resistant prostate cancer cells was associated with increased MED1 pT1457 and demonstrated continued sensitivity to THZ1." (PMID 33384381, 2021). "MED1 is associated with some biological process such as prostate cancer cell growth." (PMID 29170526, 2017). "Furthermore, MED1 was found to be linked to prostate cancer." (PMID 37511575, 2023). "Moreover, MED1 serves as a hub for nuclear receptors such as the estrogen (ER) or androgen receptor and has been linked to altered hormone receptor signaling in breast and prostate cancer." (PMID 28367434, 2017). "Elevated Med1 protein expression promotes cancer growth in hormone-dependent breast and prostate cancers." (PMID 38708315, 2024). "Hyperactive AR, in association with critical coactivators such as p300, BRD4, and MED1, drives prostate cancer progression." (PMID 37644036, 2023). "To investigate the phosphorylation status of AR and MED1 as a consequence of methyl-PP2A-C loss and the resultant bias in PP2A heterotrimer formation upon LCMT1 silencing, we employed a panel of prostate cancer cell lines stably expressing shRNA to LCMT1." (PMID 37644036, 2023). "We found that the CRPC samples had significantly higher staining of pMED1 than the ADPC and normal prostate samples, suggesting that MED1 phosphorylation increases during prostate cancer progression to the lethal phase." (PMID 35394046, 2022). "This study therefore places sd/miR-1291 as a tumor-suppressing sdRNA that regulates the MED1 oncogene to restrict prostate cancer progression." (PMID 36009366, 2022). "Next, we analyzed TCGA prostate cancer data and found that the expression of CDK9 and MED1 was positively correlated in prostate cancer." (PMID 35394046, 2022). "Since MED1 phosphorylation is significantly increased during prostate cancer progression, we proposed that pharmacological inhibition of CDK9 can block MED1 phosphorylation, transcription recycling and CRPC growth." (PMID 35394046, 2022). "Although previous studies have found that PI3K/AKT phosphorylates MED1 in prostate cancer cells, AKT1 and AKT2 are mainly localized outside of the nucleus." (PMID 35394046, 2022). "The Mediator subunit MED1 has been described to promote androgen-dependent AR activity through interaction with the ligand-binding domain of AR, and is overexpressed in prostate cancer." (PMID 33513133, 2021). "MED1 is overexpressed in prostate cancer cells where it acts as an essential coactivator for AR-mediated transcription, and its knockdown results in cell-cycle arrest, decreased proliferation, and increased cell death." (PMID 33384381, 2021). "In contrast, MED1 hyperactivity was described in breast and prostate cancer, likely due its function as a hub for nuclear hormone receptors." (PMID 28367434, 2017). "Ectopic MED1 overexpression in prostate cancer xenografts significantly promoted tumor growth in nude mice." (PMID 25481872, 2015). "MED1 expression is upregulated in the epithelium of clinically localized human prostate cancer and in CRPC cell lines." (PMID 25481872, 2015). "A recent study showed that MED1 plays an essential role in chromatin looping at the castration-resistant prostate cancer-specific AR target UBE2C gene locus." (PMID 23887938, 2013). "One recent study also reported that the hypermethylation of the miR-205 locus was strongly correlated with decreased miR-205 expression and increased MED1 expression in primary prostate cancer samples, hypoxic primary human trophoblasts, and obesity/hyperleptinemia-induced tamoxifen resistance." (PMID 39682180, 2024).
prostate carcinoma (continued). "Importantly, MED1 phosphorylation is significantly increased during prostate cancer progression to the lethal castration-resistant phase [castration-resistant prostate cancer (CRPC)]." (PMID 35394046, 2022). "MED1 has previously been shown to be a marker of poor prognosis for prostate cancer." (PMID 36009366, 2022). "Through downregulating MED1, miR-1291 hinders cell viability and invasion in prostate cancer." (PMID 34187569, 2021). "Our previous studies have found that the coactivator MED1, a subunit of an evolutionarily conserved multiprotein complex (∼30 subunits) known as the Mediator, is essential for androgen-regulated transcription in prostate cancer cells." (PMID 31501863, 2019). "Recently, the role of MED1 in prostate cancer oncogenesis and progression has gained recognition." (PMID 25481872, 2015). "Thus, for instance, FOXA1 (Forkhead box protein A1), another member of the forkhead box protein family, was found bound in the exon 3 region of UBE2C gene and, in association with MED1 (mediator complex subunit 1), was capable of altering UBE2C expression levels in prostate cancer cells." (PMID 29596365, 2018). "For example, CDK7 is an important regulator of both factors, at least in part because it phosphorylates MED1 to enhance AR- and MYC-regulated transcription in prostate cancer." (PMID 40163908, 2025). "For example, CDK7 phosphorylates Threonine 1457 (T1457) of the Mediator Complex Subunit 1 (MED1), which is upregulated in prostate cancer cells." (PMID 40163908, 2025). "Some Mediator complex subunits, such as MED1 and MED19, are cofactors of AR and enhance its transcriptional activity in prostate cancer." (PMID 39253786, 2024). "Treatment of prostate cancer cells with enzalutamide enhances recruitment of pioneer factor GATA2, AR, Mediator subunits MED1 and MED14, and RNA Pol II to regulatory elements of enzalutamide-responsive genes." (PMID 31501863, 2019). "Previous studies have indicated that epigenetic markers and collaborating transcription factors can be ascribed to androgen-independent prostate cancer, including histone markers, FoxA1, MED1(Mediator complex subunit 1) and FOXO1." (PMID 25481872, 2015). "Collectively, these data suggest MED1 plays an essential role in the ARv567es induction of UBE2C and subsequent prostate cancer cell growth in an androgen-independent manner." (PMID 25481872, 2015). "In LnCAP prostate cancer cells, FOXA1 and GATA2 independently bind to the ABCC4 gene and recruit chromatin loop-forming factors such as MED1 from distal sites to the cluster two region, allowing androgen receptors to bind and promote transcription upon hormone stimulation." (PMID 39114357, 2024). "Here, the authors show that decreased methylation of PP2A catalytic C subunit caused by loss of LCMT-1 in prostate cancer abrogates the tumor suppressor activity of PP2A on AR/MED1-dependent gene expression, proposing decreased methyl-PP2A-C as a prognostic marker for prostate cancer progression." (PMID 37644036, 2023). "Importantly, MED1 phosphorylation increases during prostate cancer progression to the lethal phase, and pharmacological inhibition of CDK9 decreases prostate tumor growth by decreasing MED1 phosphorylation and Pol II recycling." (PMID 35394046, 2022). "It has been reported that phospho-MED1 mediates UBE2C locus looping in castration-resistant prostate cancer cells, but not in the androgen-dependent prostate cancer cells." (PMID 25481872, 2015). "Given that CCAR1 is required for optimal recruitment of MED1 to AR-binding sites, it will be interesting to test whether CCAR1 also contributes to UBE2C locus looping and castration-resistant prostate cancer progression." (PMID 23887938, 2013).
prostate carcinoma (continued). "In prostate cancer cells miR-205 transcription is repressed, due to hypermethylation of the MIR-205 locus, which leads to a decrease in miR-205 expression and therefore to an increase in MED1 expression, since miR-205 is able to target MED1 mRNA and reduces its expression." (PMID 35205279, 2022). "Our results suggest that GATA2 directs enzalutamide-induced transcription by recruiting AR, MED1/MED14, and Pol II to regulatory elements of enzalutamide-responsive genes, revealing a novel role of GATA2 in directing antagonist-mediated transcription in prostate cancer." (PMID 31501863, 2019).
glioma (8 papers, 2021 to 2024). A benign or malignant brain and spinal cord tumor that arises from glial cells (astrocytes, oligodendrocytes, ependymal cells). "Additionally, both MED1 and Myc were markedly upregulated in human glioma, associated with advanced histological grade in glioma patients." (PMID 34696771, 2021). "Experimental evidence suggests that inhibiting CDK7 significantly mitigates the recruitment of MED1 to super-enhancers, providing a promising strategy for glioma treatment." (PMID 38967893, 2024). "In this study, we identified the SE-driven-LIMD1-AS1 in glioma cells by H3K27ac and MED1 ChIP-seq and SE-driven-LIMD1-AS1 high expression in glioma tissues and correlated with shorter survival times of patients." (PMID 37385987, 2023). "Firstly, the inhibition of CDK7 decreased the mRNA expression of MED1 in LN-18 and T98G glioma cells." (PMID 37385987, 2023). "Most importantly, CDK7 significantly correlated with MED1 expression in glioma tissues from the TCGA and CGGA database." (PMID 37385987, 2023). "In summary, our findings provide solid evidence to support the idea that epigenetic activation of TMEM44-AS1 mediated by MED1 promotes glioma progression through the Myc positive feedback loop." (PMID 34696771, 2021). "Immunofluorescence imaging revealed that Myc mainly colocalized with MED1 in the nucleus of LN-18 and U251 glioma cells." (PMID 34696771, 2021). "In addition, ChIP-seq showed enrichment of SE-enriched transcriptional coactivators BRD4 and MED1 at the LINC02454 locus in U87 glioma cells." (PMID 38177123, 2024). "It forms a positive feedback loop with Myc/MED1, affecting tumor development in glioma." (PMID 37561335, 2024). "Furthermore, endogenous CDK7 coimmunoprecipitated with endogenous MED1 in LN-18 and T98G glioma cells." (PMID 37385987, 2023). "Together, these data indicated that MED1 might be involved in the function of CDK7 as an epigenetic activator of LIMD1-AS1 in glioma cells." (PMID 37385987, 2023). "Together, these data indicated that MED1 might be involved in the function of Myc as an epigenetic activator of TMEM44-AS1 in glioma cells." (PMID 34696771, 2021). "Most importantly, Myc was also significantly correlated with MED1 expression in glioma." (PMID 34696771, 2021). "Moreover, we found that Myc increased the binding of MED1 across the TMEM44-AS1 super-enhancer in SF126 glioma cells." (PMID 34696771, 2021). "However, it is necessary to observe whether a hypersensitive subset can be identified through phospho-MED1 levels in glioma hypersensitive to CDK7 inhibition." (PMID 37385987, 2023). "Activation of CDK7 significantly enhances the recruitment of MED1 to the super-enhancer of LIMD1-AS1, thereby enhancing the expression of LIMD1-AS1 and promoting glioma cell proliferation." (PMID 38967893, 2024). "Several studies have demonstrated that MED1, as a constituent of SEs, plays a pivotal role in HNSC and gliomas." (PMID 39343952, 2024). "Recently, we reported that MED1 and Myc interact to regulate SEs of TMEM44-AS1 and promote their glioma cell-specific transcriptional activation." (PMID 37501079, 2023). "We examined the subcellular location of CDK7 and MED1 using immunofluorescence staining and found that CDK7 mainly colocalized with MED1 in the nucleus of LN-18 and T98G glioma cells." (PMID 37385987, 2023). "Our results confirmed that inhibition of CDK7 attenuates MED1 recruitment to the super-enhancer of LIMD1-AS1 and then decreases the expression of LIMD1-AS1 in glioma cells." (PMID 37385987, 2023). "To further verify whether MED1 is involved in epigenetic activation of LIMD1-AS1 induced CDK7, we observed LIMD1-AS1 expression after co-transfection of si-MED1 and CDK7 to SF126 glioma cells." (PMID 37385987, 2023). "To further verify whether MED1 mediated epigenetic activation of TMEM44-AS1 induced Myc, we observed TMEM44-AS1 expression after co-transfection of si-MED1 and Myc to SF126 glioma cells." (PMID 34696771, 2021).
glioma (continued). "We found that the inhibition of CDK7 decreased the binding of MED1 across the LIMD1-AS1 super-enhancer, but not the promoter, in LN-18 and T98G glioma cells." (PMID 37385987, 2023). "MED1 could directly bind to the TMEM44-AS1 super-enhancer in LN-18 and U251 glioma cells, but not promoter." (PMID 34696771, 2021).
colorectal cancer (6 papers, 2011 to 2022). A primary or metastatic malignant neoplasm that affects the colon or rectum. "In research of colorectal cancer and ovarian cancer, the mutation of MED1 associated with microsatellite instability of cancer cells, which promoted tumorigenesis." (PMID 35769811, 2022). "Mutations and inactivation of MED1 is reported to activate tumorigenesis in colorectal cancer and various carcinomas." (PMID 33251127, 2020). "Mutations and single nucleotide polymorphisms (SNPs) in BER genes are associated with numerous cancers, such as UNG2 (uracil DNA glycosylase) mutations in glioblastoma, MED1 (mediator complex subunit 1) mutations in colorectal cancer, and OGG1 (8-oxoguanine DNA glycosylase) mutations in lung cancer." (PMID 26967246, 2016). "Using Med1 ChIP‐seq data, we identified ~ 3,500 typical and 214 super‐enhancers in LoVo colorectal cancer cells." (PMID 33502116, 2021). "The promoter region of MED1 (mediator complex subunit 1), one of the optimized aberrant methylated gene associated with cancers, was reported to be frequently methylated in ovarian and colorectal cancer cell lines and this had been to result in the low expression of MED1." (PMID 21985575, 2011).
lung carcinoma (6 papers, 2016 to 2024). "MED1, a subunit of the tail module, was described to negatively modulate expression of metastasis-related genes and to be downregulated in melanoma and lung cancer." (PMID 28367434, 2017). "Whereas in other cancer entities such as melanoma, lung cancer as well as BCa downregulation of MED1 increases tumorigenic potential by modulating metastasis-related genes like uPAR." (PMID 28367434, 2017).
Hepatic steatosis (5 papers, 2010 to 2023). Steatosis is a term used to denote lipid accumulation within hepatocytes. "Med1 deficient livers fail to develop hepatic steatosis induced by glucorcorticoid receptor (GR) agonist and also fail to develop hepatic steatosis when induced by PPARγ overexpression (unpublished data)." (PMID 20814439, 2010). "MED1-knockout mice that receive a HFD for up to 4 months fail to develop fatty liver, whereas mice with MED1 that receive a HFD develop severe hepatic steatosis." (PMID 36726725, 2023). "As reported, the coactivator mediator subunit MED1 is the only coactivator required for PPARγ-stimulated hepatic steatosis." (PMID 28611668, 2017). "The coactivator mediator subunit MED1 is the only coactivator that is required for PPARγ-stimulated adipogenic hepatic steatosis in mice." (PMID 28611668, 2017).
melanoma (5 papers, 2016 to 2023). A malignant, usually aggressive tumor composed of atypical, neoplastic melanocytes. "In melanoma, downregulation of the tail module MED1, also known as TRAP220, triggers a strong tumorigenic phenotype and is associated with worse outcome in lung adenocarcinoma." (PMID 28367434, 2017). "The analysis demonstrated consistent medium levels of MED1 expression in the nuclei of all melanocytic cells of benign dermal and compound nevi, whereas expression in the nuclei of melanomas was much more inconsistent, including specimens with high, medium, or low/no expression." (PMID 31695025, 2019). "Thus, we quantified MED1 levels in a panel of benign nevi (n = 39) and melanoma tumors (n = 74) using immunohistochemical staining." (PMID 31695025, 2019). "In melanoma, MED1 and MED14 was increased, while MED4 was reduced." (PMID 31695025, 2019). "Interestingly, in two independent studies, siRNA-mediated knockdown of MED1 in melanoma and non-small cell lung cancer cells led to enhanced invasive properties in vitro by modulating metastasis-related genes such as the urokinase receptor/uPAR." (PMID 28367434, 2017). "Immunohistochemical staining of MED1 showed that 31% and 27% of melanoma specimens exhibited high or low/no expression, respectively." (PMID 31695025, 2019). "Indeed, immunostaining of melanoma tumors, which often express SSX proteins, exhibited altered levels of MED1 compared to benign nevi." (PMID 31695025, 2019).
Obesity (5 papers, 2007 to 2024). Accumulation of substantial excess body fat. "Our study implicates Med1 as an important coactivator mediating the biological effects of obesity, as 48 out of 74 genes coining the obesity-associated gene signature are putative targets for Med1 recruitment." (PMID 34389732, 2021). "We present Med1, an important subunit of the human mediator complex, as the key node of leptin action that associates with obesity-signature genes." (PMID 34389732, 2021). "Furthermore, in silico analysis revealed that coactivator Med1 potentially associates with 48 (out of 74) obesity-signature genes." (PMID 34389732, 2021). "Consequently, Med1 MKO mice are resistant to high-fat diet (HFD)-induced obesity and display enhanced insulin sensitivity and improved glucose tolerance." (PMID 38690566, 2024).